FLACC1 (flagellum associated containing coiled-coil domains 1)
Synonyms: ALS2CR12
Tractability: Antibody: the Human Protein Atlas places it where antibodies can reach. PROTAC: ubiquitination databases record sites on it.
Gene: Protein-coding gene on chromosome 2 (201,288,271 to 201,357,398, reverse strand). Ensembl gene ENSG00000155749.
Subcellular location: Cytoplasm; Cytoplasmic granule; Cell projection, cilium, flagellum
Subcellular location (Human Protein Atlas): Annulus; Connecting piece; Cytosol; Mid piece; Plasma membrane
Gene Ontology:
Molecular function: protein binding
Cellular component: cytoplasm; cytoplasmic vesicle; outer dense fiber; sperm flagellum; motile cilium
Genetic constraint (gnomAD): Loss-of-function variants: 63 observed, 64.5 expected, observed/expected ratio (o/e) 0.98, 90% interval 0.8 to 1.21. The upper end of that interval is the gene's LOEUF score, 1.21, which puts it in group 5 of 6, group 1 being the genes least tolerant of losing a copy. Missense variants: 449 observed, 509.4 expected, observed/expected ratio (o/e) 0.88, 90% interval 0.81 to 0.95. Synonymous variants: 155 observed, 170.46 expected, observed/expected ratio (o/e) 0.91, 90% interval 0.8 to 1.04.
Homologues: Orthologues: chimpanzee FLACC1 (98% identical), macaque FLACC1 (92% identical), rabbit FLACC1 (74% identical), dog FLACC1 (73% identical), rat Flacc1 (64% identical), pig FLACC1 (60% identical), mouse Flacc1 (58% identical), tropical clawed frog flacc1 (24% identical), Caenorhabditis elegans pals-6 (13% identical), Caenorhabditis elegans pals-27 (11% identical), Caenorhabditis elegans pals-26 (11% identical), Caenorhabditis elegans pals-13 (10% identical), and 3 more.
Diseases named in the same sentence as FLACC1 in open-access papers:
FLACC1 is named in the same sentence as 9 diseases in open-access papers, as found by Europe PMC text mining. Sharing a sentence is not in itself a finding about the gene and the disease. The quoted sentences say what the papers report.
melanoma (2 papers, 2024 to 2026). A malignant, usually aggressive tumor composed of atypical, neoplastic melanocytes. "Both also provide some support for FLACC1, where in contrast to the CASP8 eQTL, higher FLACC1 levels are associated with the melanoma risk allele." (PMID 41542517, 2026). "Consistent with observed FLACC1 QTLs, melanocyte-specific capture-C and 3C assays showed a physical interaction between fine-mapped melanoma risk variants and the FLACC1 promoter region suggesting risk variants indeed may play a role in regulating both genes." (PMID 41542517, 2026). "TWAS of melanoma risk using mammary and skin tissues found both CASP8 and FLACC1 to be significant TWAS genes with the same direction of effect observed in melanocytes." (PMID 41542517, 2026). "Here, we confirmed a physical interaction between these variants and the FLACC1 promoter in both melanocyte cultures, with little evidence of a strong association in melanoma cells." (PMID 41542517, 2026). "In TCGA melanomas, we observed an FDR-significant eQTL for FLACC1 (P = 6.57 × 10−4), as well marginal eQTLs for CASP8 (P = 6.82 × 10−3) and TRAK2 (P = 0.03)." (PMID 41542517, 2026). "Collectively, these data suggest that the melanoma GWAS signal may be explained by cis-regulation of CASP8 and FLACC1, with opposite directions of effect for the two genes." (PMID 41542517, 2026).
breast invasive carcinoma (1 paper, 2026). "We note similarly complex patterns of correlation between both risk- and protective- allele rs3769823 binding proteins in non-melanocytic tissues (GTEx skin, GTEx breast mammary, and TCGA breast invasive carcinoma) and expression of CASP8 as well as FLACC1." (PMID 41542517, 2026).
cancer (6 papers, 2020 to 2026). A tumor composed of atypical neoplastic, often pleomorphic cells that invade other tissues. "Our results indicate that the top credible causal set variant rs3769823 likely influences expression of CASP8 and FLACC1 in a cell-type specific manner and may be a relevant functional variant for multiple cancers associated with this locus." (PMID 41542517, 2026).
FLACC1 also shares sentences with these, for which no sentence is quoted: lung carcinoma (3 papers); breast carcinoma (2); amyotrophic lateral sclerosis (1); esophageal cancer (1); infection (1); lateral sclerosis (1).